CDC73 (cell division cycle 73)
Diseases named in the same sentence as CDC73 in open-access papers (continued):
Sharing a sentence is not in itself a finding about the gene and the disease.
parathyroid tumors (continued). "Inactivating mutations in CDC73 were first discovered in hyperparathyroidism-jaw tumor syndrome (HPT-JT), an autosomal dominant genetic disease featuring parathyroid tumors with fibro-osseous jaw tumors as well as uterine and renal lesions." (PMID 40881643, 2025). "It is difficult to detect the CDC73 status of parathyroid neoplasms before surgery, as fine needle aspiration of parathyroid tumors was not recommended to avoid tumor rupture, seeding and bleeding." (PMID 36010997, 2022). "Mutations on CDC73, MEN1, HIC1, EZH2, and β-catenin genes, demonstrated to be involved in parathyroid tumors, seem to implicate epigenetic modifications in their mechanism of tumorigenesis." (PMID 35628190, 2022). "Hahn and colleagues demonstrated global loss of H2Bub1 in familial and sporadic parathyroid tumours associated with mutation of a gene encoding a member of the PAF1C, CDC73." (PMID 33233707, 2020). "Parathyroid tumours were found to occur in 68% of Cdc73+/− mice, and 25% of these were adenomas and 75% were APAs (defined by having collagenous fibrous septa, and/or immunostaining for galectin-3 but lacking evidence of invasion or metastasis)." (PMID 28288139, 2017). "Parathyroid tumours in Cdc73+/−, Cdc73+/L/PTH-Cre and Cdc73L/L/PTH-Cre mice had significantly increased proliferation, with rates >fourfold higher than that in parathyroid glands of wild-type littermates (P<0.0001)." (PMID 28288139, 2017). "On the other hand, genetic testing for germline CDC73 variants should be considered in all parafibromin negative parathyroid tumours." (PMID 38396977, 2024). "In this study, we report that Finnish PHPT patients with CDC73 mutation-negative parathyroid tumors frequently display rare germline mutations in the PRUNE2 tumor suppressor gene." (PMID 36900197, 2023). "Moreover, 75% of the parathyroid tumours were APAs, and thus these Cdc73+/− mice with the conditional Cdc73+/L/PTH-Cre and Cdc73L/L/PTH-Cre mice provide important in vivo models for this rare but difficult to treat human neoplasm." (PMID 28288139, 2017). "However, it is important to note that the Cdc73+/− mice developed two of the most common tumours, namely parathyroid tumours and uterine neoplasms that are observed in HPT-JT patients." (PMID 28288139, 2017). "The carcinomas displayed copy number alterations in agreement with previous studies, whereas the CDC73-mutated adenomas did not display the same pattern of alterations at loci frequently deleted in unselected parathyroid tumors." (PMID 23029479, 2012). "Thus, the CDC73 status plays a vital role in the diagnosis and management of parathyroid tumors." (PMID 40881643, 2025). "CDC73 thus could represent a potential additional gene influencing the phenotypic spectrum of MEN syndromes, particularly regarding hyperparathyroidism associated with parathyroid gland neoplasms." (PMID 39336996, 2024). "The molecular pathogenesis of parathyroid tumors has already been partly elucidated; Heppner and Carling have reported that inactivating somatic mutations of tumor suppressor genes multiple endocrine neoplasia type 1 (MEN1), RET, and HRPT2/CDC73 have been identified in parathyroid tumors." (PMID 35879975, 2022). "Most studies therefore seem to agree that almost all parathyroid tumors with wild-type CDC73 sequence display a diffuse positive parafibromin stain, while reduced or absent nuclear parafibromin expression is an aberrant staining pattern and might signal the presence of a mutation." (PMID 33269427, 2021). "Benign parathyroid tumours with wild-type CDC73 did not demonstrate loss of H2Bub1." (PMID 33233707, 2020). "However, no studies have yet analyzed CDC73-mutated parathyroid tumors using concurrent genome-wide high-resolution array comparative genomic hybridization (a-CGH) or single nucleotide polymorphism (SNP) microarray-based loss of heterozygosity (LOH)." (PMID 23029479, 2012).
parathyroid tumors (continued). "In silico analysis showed that these three miRNAs directly targeted genes associated with the development of different inheritable forms of parathyroid tumors (i.e., CCND1, RET, CDKN1B, RB1, VDR, PRDM2, CDKN2C, and CDC73/HRPT2 genes)." (PMID 33066578, 2020). "Cdc73+/−, Cdc73+/L/PTH-Cre and Cdc73L/L/PTH-Cre mice developed parathyroid tumours, which had nuclear pleomorphism, fibrous septation and increased galectin-3 expression, consistent with atypical parathyroid adenomas, from 9 months of age." (PMID 28288139, 2017). "Mice with a parathyroid-specific deletion of Cdc73, the gene involved in JT-HPT syndrome, developed parathyroid tumors from 9 months of age, which showed nuclear pleomorphism, fibrous septation, and increased galectin-3 expression, consistent with atypical parathyroid adenomas associated with PHPT." (PMID 39409111, 2024). "Given the identification of the MEN1, RET, and CDC73 gene aberrancies as main responsible for the development of familial PHPT, numerous studies followed in which the involvement of these genes were assessed in sporadic parathyroid tumors." (PMID 33269427, 2021). "Previous studies using conventional CGH and LOH studies reported frequent losses on chromosome 1p in parathyroid tumors regardless to the CDC73 status and for which no candidate genes have been found." (PMID 23029479, 2012). "The expression levels of CDC73 and CDKN1B/p27, interacting with molecules involved in WNT/β-catenin and parathyroid-specific pathways and modulated by epigenetic mechanisms like lncRNAs and histone-related methylation, may determine the heterogeneity of the clinical features of parathyroid tumors." (PMID 39409111, 2024).
parathyroid adenomas (29 papers, 2010 to 2025). "In the present study, the germline variant c.1155-3A > G located within intron 13 of the CDC73 gene was identified in two family members with PHPT due to solitary parathyroid adenomas." (PMID 39677927, 2025). "When pathologists discuss parafibromin, it is typically in the context of diagnosing an atypical parathyroid tumor or parathyroid carcinoma, as these conditions are more frequently associated with CDC73 gene mutations compared to parathyroid adenomas." (PMID 38363524, 2024). "A germline mutation (deletion) in CDC73/HRPT2 gene was verified in 35% of patients with sporadic parathyroid adenoma by real-time PCR." (PMID 37223014, 2023). "The case study was conducted to document a rare familial case of PHPT arising from parathyroid adenoma with brown tumors in both a father and his daughter, and genetic testing revealed CDC73 gene mutations in both." (PMID 37807045, 2023). "We report a familial case in which father and daughter were diagnosed to have brown tumors due to parathyroid adenoma and ectopic parathyroid adenoma, and genetic testing revealed CDC73 gene mutations in both." (PMID 37807045, 2023). "The rates of CDC73 mutation and parafibromin loss decrease from parathyroid adenoma to atypical adenoma to carcinoma." (PMID 36211470, 2022). "The target-PPI included differentially methylated genes as well as parathyroid adenoma susceptible genes (CDC73, MEN1, CCND1, RET)." (PMID 35879975, 2022). "HPT-jaw tumor (JT) syndrome, which is associated with recurrent functional parathyroid adenomas as well as behavioral issues, has been shown to be associated with a large-scale 1q31 deletion, specifically the CDC73 gene." (PMID 29739732, 2019). "CDC73 gene mutations in parathyroid adenomas seem rare, but are reported, especially in cystic or atypical adenomas." (PMID 23029479, 2012). "The presence of the CDC73 mutation in about half of the patients with PC reported in the literature, together with its rare occurrence in parathyroid adenomas, indicates that it might be involved in PC development and predicts a malignant behavior." (PMID 24145611, 2013). "Our data could suggest that CDC73-mutated parathyroid adenomas exhibit a partly unique cytogenetic profile in addition to that of carcinomas and unselected adenomas." (PMID 23029479, 2012). "However, the frequency of CDC73 mutations in sporadic parathyroid adenomas is low, at 0–4 %, indicating that CDC73 mutations likely confer an aggressive growth potential and may result in malignant transformation of parathyroid cells." (PMID 27658992, 2016). "According to various studies, CDC73, MEN1, CCND1, and RET were shown to be parathyroid adenoma susceptible genes." (PMID 35879975, 2022). "The tumor suppressor gene CDC73 was found to be associated with hyperparathyroidism-jaw tumor syndrome (HPT-JT), which is characterized by parathyroid adenoma or carcinoma, ossifying fibroma (OF) of the jaws, and renal and uterine lesions." (PMID 27658992, 2016). "Mutations in the hyperparathyroidism type 2 (HRPT2/CDC73) gene and alterations in the parafibromin protein have been established in the majority of parathyroid carcinomas and in subsets of parathyroid adenomas." (PMID 23029479, 2012). "CDC73 variants were identified in 12.4% of referred PHPT patients, with HPT-JT syndrome in 3.3%, familiar isolated PHPT in 5.6%, apparently sporadic PC in 2.2% and apparently sporadic parathyroid adenoma in 1.1%." (PMID 36284286, 2022). "Thus, cell division cycle 73 (CDC73) germline mutations cause HPT‐JT, and CDC73 mutations occur in 70% of sporadic PC, but in only ∼2% of parathyroid adenomas." (PMID 28881068, 2017). "Positive controls (normal parathyroid tissue and sporadic parathyroid adenoma without CDC73 mutations) exhibited an intense nuclear and cytoplasmic positivity." (PMID 24842573, 2014).
parathyroid adenomas (continued). "Here we report the genetic and molecular analysis of the CDC73/HRPT2 gene in three patients affected by PHPT due to atypical and typical parathyroid adenomas, in one case belonging to familial PHPT." (PMID 24340015, 2013). "Moreover, while somatic CDC73 gene mutations have been reported in small subsets of sporadic parathyroid adenomas, no reports on somatic RET gene mutations in parathyroid adenoma have been noted." (PMID 33269427, 2021).
adenoma (19 papers, 2008 to 2025). A neoplasm arising from the epithelium. "Patient 3 and patient 4, whose tumors were classified as adenoma-type APTs, also had a CDC73 missense variant (c.1582C>T and c.742A>G, respectively)." (PMID 40434298, 2025). "Mutated/decreasedTumor suppressor protein encoded by CDC73 gene.Function: repression of cyclin D1 (cell cycle halt).Detectable by IHQ.1–6% overlap in mutations with PT adenomas." (PMID 40149663, 2025). "CDC73/HRPT2 gene is rarely involved in sporadic disease, while its mutant allele, caused by germline mutations, is detected in cystic and large adenomas and in recurrent cases." (PMID 37223014, 2023). "Quantitative PCR-based copy number loss regarding CDC73 was observed in three adenomas, while all the carcinomas were diploid or showed copy number gain for CDC73 gene." (PMID 23029479, 2012). "As of this, our conclusions regarding CDC73 mutated adenomas and their partly unique cytogenetic profile as compared to CDC73 wild-type cases are based on the comparison between our current findings and previously published data from this group and others." (PMID 23029479, 2012). "Somatic mutation of CDC73 is present in 70% of PCs and rarely in benign sporadic adenomas (0.8%)." (PMID 34659402, 2021). "Interestingly, these three CDC73-mutated adenomas have previously been shown to exhibit loss of parafibromin expression using Western blot and immunohistochemistry, thereby providing a plausible explanation for the lack of parafibromin in these cases with two separate hits." (PMID 23029479, 2012). "Inactivating mutations of the tumour suppressor CDC73/HRPT2 gene have been found in HPT-JT patients and also as genetic determinants of sporadic parathyroid carcinoma/atypical adenomas and, rarely, typical adenomas, in familial PHPT." (PMID 24340015, 2013). "A qPCR-based DNA copy number analysis displayed only one copy of the CDC73 gene in three of the adenomas (T2, T3 and T4)." (PMID 23029479, 2012). "Here we report the identification and the functional characterization of three different CDC73 mutations located within NoLS 76-92, found in three subjects affected by PHPT due to parathyroid atypical adenoma or typical adenoma, the latter belonging to familial PHPT." (PMID 24340015, 2013). "Unsupervised whole genome clustering clearly clustered the carcinomas into one group, further confirming the different genetic profile of the carcinomas compared to the non-malignant CDC73-mutated adenomas." (PMID 23029479, 2012). "Furthermore, CDC73-mutated carcinomas displayed losses at 1p and 13 which are not seen in CDC73-mutated adenomas, making these regions of interest for further studies regarding malignant properties in tumors from CDC73-mutated cases." (PMID 23029479, 2012). "In addition, CDC73-mutated carcinomas display loss at 1p and 13 which is not seen in CDC73-mutated adenomas, perhaps providing clues to loci involved in malignant transformation." (PMID 23029479, 2012). "Furthermore, even though the sample size in this study was limited, we could see a statistically significant difference regarding loss at chromosomes 1p and 13 in CDC73 mutated carcinomas as opposed to CDC73 mutated adenomas." (PMID 23029479, 2012). "Another weakness in this study is the fact that no CDC73 wild-type adenomas were included for a-CGH analyses." (PMID 23029479, 2012).
Hyperparathyroidism-jaw tumor syndrome (16 papers, 2009 to 2025). "Germline mutations in CDC73 are closely associated with hyperparathyroidism-jaw tumor syndrome (HPT-JT), which lead to the loss of parafibromin, a kind of protein consisting of 531 amino acids." (PMID 40038693, 2025). "Hyperparathyroidism-jaw tumor syndrome (HPT-JT) is a hereditary neoplastic disorder caused by a pathogenic variant in the CDC73 tumor suppressor gene." (PMID 40115416, 2025). "Hyperparathyroidism-jaw tumor syndrome (HPT-JT) is an autosomal dominant genetic disorder that involves mutations in the cell division cycle (CDC73) gene." (PMID 36011051, 2022). "Hyperparathyroidism-jaw tumor syndrome (HPT-JT) is an early onset and highly penetrant autosomal dominant disease due to mutation of the HRPT2/CDC73 gene located on 1q25-31." (PMID 35454175, 2022). "This may contribute to tumor suppressor activity attributed to CDC73, which is mutated in hyperparathyroidism-jaw tumor syndrome (HPT-JT), exhibiting a loss of function mutation in more than 80% of these malignancies." (PMID 29774127, 2018). "Among BFOLs, two diseases have been well-characterized, fibrous dysplasia (FD) and hyperparathyroidism-jaw tumor syndrome (HPT-JT) (OMIM:145001), caused by specific gene mutations, GNAS and HRPT2/CDC73, respectively." (PMID 35454175, 2022).
primary hyperparathyroidism (12 papers, 2014 to 2025). "Further studies showed primary hyperparathyroidism and genetic analysis revealed a CDC73 mutation (initially HRPT2)." (PMID 29181209, 2017). "CDC73 mutations have been detected in between 0 and 33 % of individuals with familial isolated primary hyperparathyroidism." (PMID 27658992, 2016). "Moreover, CDC73 mutation carriers should be also periodically screened for primary hyperparathyroidism and the other associated tumors." (PMID 31929790, 2019). "Here, we report a heterozygous c.1138C>T (p.Leu380Phe) CDC73 germline variant in a clinically diagnosed MEN1 patient, based on combined occurrence of primary hyperparathyroidism, acromegaly, and a PNEN." (PMID 33150274, 2020). "Eleven members (six affected with primary hyperparathyroidism and five unaffected) were ascertained from the family, and multiplex ligation-dependent probe amplification was performed to detect CDC73 deletion using leukocyte DNA." (PMID 24823466, 2014). "Thus, Cdc73+/− mice over 17 months of age had features of primary hyperparathyroidism." (PMID 28288139, 2017).
familial isolated hyperparathyroidism (10 papers, 2012 to 2025). A rare, autosomal dominant hereditary syndrome characterized by hypercalcemia, abnormally high levels of parathyroid hormone, and isolated hyperfunctioning parathyroid tumors. "Constitutional CDC73 gene mutations are also associated with a subset of families presenting with familial isolated hyperparathyroidism (FIHP)." (PMID 23029479, 2012). "Non-syndromic hereditary hyperparathyroidism, called familial isolated hyperparathyroidism (FIHP), can be caused by the incomplete manifestation of mutations of syndrome-related genes such as MEN-1, CDC73, GCM2, CDKN1A, CDKN1B, or CDKN2C." (PMID 36900197, 2023). "Inactivating mutations of CDC73 cause Hyperparathyroidism-Jaw Tumour syndrome (HPT-JT), Familial Isolated Hyperparathyroidism (FIHP) and sporadic parathyroid carcinoma." (PMID 28774260, 2017). "Familial isolated hyperparathyroidism (FIHP) may be due to incomplete penetrance of mutations causing syndromic PHPTs, as the genes found in FIHP overlap, for example, MEN1, CDC73, or CASR." (PMID 38038882, 2024).
Wilms tumor (8 papers, 2015 to 2025). An embryonal neoplasm characterized by the presence of epithelial, mesenchymal, and blastema components. "Moreover, germline mutations that predispose individuals to Wilms tumor are also found in genes that converge into similar pathways, such as CDC73 and CTR920." (PMID 39009564, 2024). "CDC73 is an established Wilms tumour predisposition gene but, to our knowledge, has not previously been associated with familial Wilms tumour." (PMID 30885698, 2019). "A further five constitutionally mutated genes—PIK3CA, FBXW7, ASXL1, BRCA2, and CDC73—were somatically mutated in other cancer types but have not been proven to be somatic drivers in Wilms tumour." (PMID 30885698, 2019). "Together, these data suggest that the mutations in CDC73 and CTR9 found in patients with hyperparathyroidism-jaw tumor syndrome and some patients with Wilms tumors, respectively, may contribute to cancer progression by contributing to genome instability." (PMID 29320491, 2018).
ossifying fibroma (7 papers, 2014 to 2025). A bone benign neoplasm that is located_in the mouth and results_in an overgrowth of gingival tissue due to irritation or trauma. "HPT-JT syndrome is caused by inactivating mutations of the HRPT2/CDC73 tumor suppressor gene and consists of ossifying fibromas of the maxilla and mandible, adenomatous polyps of the uterus, and renal tumors." (PMID 40177730, 2025). "In the present study we characterized a somatic missense mutation (i.e., Ile60Asn) located in the N-terminal domain of CDC73, identified in a mandibular ossifying fibroma that occurred in a HPT-JT patient." (PMID 24842573, 2014).
colorectal cancer (6 papers, 2016 to 2023). A primary or metastatic malignant neoplasm that affects the colon or rectum. "CDC73 is underexpressed in colorectal cancer and its expression is negatively related to colorectal cancer differentiation at both mRNA and protein levels." (PMID 36211470, 2022). "As a differentiation marker, ALP activity was increased in CDC73 transfectants of colorectal cancer cells." (PMID 29221126, 2017).
hyperparathyroidism 2 (6 papers, 2011 to 2022). "In 2002, germline mutation of CDC73 gene, known also as HRPT2 (hyperparathyroidism 2), was found in families affected by the autosomal dominant hyperparathyroidism-jaw tumour syndrome (penetrance 65–90%)." (PMID 35805976, 2022).
multiple endocrine neoplasia type 1 (6 papers, 2011 to 2023). An autosomal dominant tumor predisposition syndrome caused by pathogenic variants in the MEN1 gene, characterized by an increased risk of tumors of the parathyroid glands, pituitary gland, and foregut neuroendocrine tumors (most commonly pancreatic islet cells). "At a median age of 10.8 (2.0–14.4) years, 18 patients received cinacalcet for primary HPT (N = 13 inactive CASR mutation, N = 1 CDC73 mutation, N = 1 multiple endocrine neoplasia type 1, N=3 unknown etiology)." (PMID 36090548, 2022).